RBP4 (retinol binding protein 4)
Diseases named in the same sentence as RBP4 in open-access papers (continued):
Sharing a sentence is not in itself a finding about the gene and the disease.
Cirrhosis (8 papers, 2008 to 2025). A chronic disorder of the liver in which liver tissue becomes scarred and is partially replaced by regenerative nodules and fibrotic tissue resulting in loss of liver function. "We found proteins involved in hormone and vitamin transportation to be altered in patients with cirrhosis, for example, retinol‐binding protein (RBP4) and transthyretin (TTR)." (PMID 30824564, 2019). "RBP4 was demonstrated to have a prognostic significance as a marker in patients with chronic liver disease and cirrhosis-induced by genotype 1 HCV infection." (PMID 24283668, 2013). "RBP4 was also shown to have prognostic significance as a marker in patients with chronic liver disease and cirrhosis-induced by genotype 1 HCV infection." (PMID 24283668, 2013). "Among CLD patients those with c2-cirrhosis (ethanol-induced) showed lowest RBP4 values compared to CLD patients with fibrosis or hepatic cancer (P < 0.001)." (PMID 18752671, 2008). "In addition, the CKG highlighted the TTR-RBP complex (TTR and RBP4) as downregulated in patients with cirrhosis compared to healthy individuals." (PMID 35102292, 2022). "RBP4, which possesses a nuclear transcription factor activator protein sequence, is mainly synthesized in the liver, and its expression can be reduced in acute liver disease, chronic hepatitis, and cirrhosis." (PMID 31396303, 2019). "Thus, the impacts of cirrhosis on RBP4 levels may vary between critically ill patients with or without underlying liver diseases." (PMID 28588245, 2017). "This parallels our plasma proteome data, in which RBP4 was clearly significant in cirrhosis but not in the NAFLD sub‐groups." (PMID 30824564, 2019). "Additionally, we confirmed that RBP4, TTR and ROH levels in various liver diseases were markedly depressed, particularly in patients with c2-cirrhosis or hepato-cellular carcinoma, which is in accordance with results of previously published studies." (PMID 18752671, 2008). "Of note, RBP4 serum concentrations remained significantly (P < 0.001, Mann-Whitney U test) elevated in controls (n = 42, median 28.1; range, 18.8-255.6 mg/L) compared to ICU patients without cirrhosis (n = 112, median 16.5, range 0.3-147.6 mg/L)." (PMID 20932285, 2010).
coronary atherosclerosis (8 papers, 2012 to 2024). Atherosclerosis of the coronary vasculature. "Considering SCH is a well-known risk factor for coronary atherosclerosis, we carried out the present study to evaluate the association of serum RBP4 concentration with the presence and severity of angiographically demonstrated CAD in patients with SCH." (PMID 31278889, 2019). "These analyses in healthy, recently postmenopausal women suggest that higher RBP4 levels are weakly associated with elevations in triglycerides, and that both low and high RBP4 levels may be associated with subclinical coronary atherosclerosis." (PMID 22587616, 2012). "Hypothyroidism seemed to mediatesome potential confounding factors and regulate coronary atherosclerosis,including serum retinol-binding protein 4, fatty liver, and coronary endothelialdysfunction." (PMID 39742251, 2024). "In early studies, we found an increase in the levels of transthyretin transport proteins and RBP4 in the blood of patients with coronary atherosclerosis compared with controls." (PMID 36361589, 2022). "But in an earlier study, an increase in the content of transthyretin, hemopexin and retinol-binding protein-4 was found in blood serum samples of patients with verified coronary atherosclerosis." (PMID 34948066, 2021). "Those striking findings suggest an interaction between RBP4 and the pathophysiological process of coronary atherosclerosis." (PMID 25142320, 2014). "Given the caution with which the coronary atherosclerosis results should be viewed, our current results in healthy midlife women only weakly support a role for RBP4 homeostasis in cardiometabolic abnormalities and cardiovascular disease." (PMID 22587616, 2012). "However, additional in-depth investigation is required to elucidate the precise mechanism governing the pathological effect of RBP4 on the progression of coronary atherosclerosis under and status of thyoid dysfunction." (PMID 31278889, 2019). "Further prospective and experimental studies are needed to delineate whether increased RBP4 may participate in the development of coronary atherosclerosis in hypothyroidism." (PMID 31278889, 2019). "Moreover, RBP4 could also promote the abnormal proliferation and migration of vascular smooth muscle cells, which is important for the formation of coronary atherosclerosis." (PMID 31278889, 2019).
hyperuricemia (8 papers, 2014 to 2026). An abnormally high level of uric acid. "Even after adjusting for insulin level plus FBG, or HOMA-IR, RBP4 remained strongly associated with hyperuricemia." (PMID 35846279, 2022). "After adjusting for potential confounders, logistic regression indicated that the risk of hyperuricemia was highest in the highest RBP4 quartile (odds ratio: 7.9, 95% confidence interval [CI]: 4.18–14.84, compared to the lowest quartile)." (PMID 35846279, 2022). "RBP4 is strongly associated with hyperuricemia, and its predictive value was higher than that of traditional predictors." (PMID 35846279, 2022). "Several small-sample studies have reported an association between RBP4 and hyperuricemia in patients with diabetes, chronic kidney disease, and MetS, but none of them focused on the general adult population." (PMID 35846279, 2022). "Using population-based data on southern Chinese adults collected in a single-center cross-sectional epidemiological survey, we found that RBP4 had a highly significant association with hyperuricemia (P<0.001)." (PMID 35846279, 2022). "This study found that RBP4 is significantly positively associated with hyperuricemia in adults and has good predictive value for the condition." (PMID 35846279, 2022). "Recent studies have shown that RBP4 expression is associated with hyperuricaemia." (PMID 39698033, 2024). "RBP4, as a single factor, had a good performance in predicting the risk of hyperuricemia." (PMID 35846279, 2022). "Association between RBP4 and hyperuricemia according to logistic regression." (PMID 35846279, 2022). "RBP4 and hyperuricemia were positively associated in all six models." (PMID 35846279, 2022). "For example, after adjusting for 21 potential confounders, the final regression model still showed that the risk of hyperuricemia in the highest RBP4 quartile was still 7.9 times higher than that in the lowest quartile, indicating a significant independent association between RBP4 and hyperuricemia." (PMID 35846279, 2022). "This is also the most important finding of this study, as it indicates that RBP4 might be useful for predicting the risk of hyperuricemia and could be used in epidemiological research on hyperuricemia in general adult populations." (PMID 35846279, 2022). "When we adjusted for all renal function indicators (including glomerular and renal tubular function; i.e., eGFR, ACR, and NAG) in regression model 6, the regression results showed that the independent association between RBP4 and hyperuricemia remained significant." (PMID 35846279, 2022). "Finally, this is the first study to evaluate the value of RBP4 for predicting the risk of hyperuricemia, and we found that RBP4 alone performed better than traditional predictors." (PMID 35846279, 2022). "Serum RBP4 level had a highly significant association with hyperuricemia (P<0.001)." (PMID 35846279, 2022). "The AUC for RBP4 predicting hyperuricemia was 0.749 (95% CI: 0.725–0.774, P<0.001) and Youden’s index was 0.36, with an optimum cutoff of 54.5 mg/L." (PMID 35846279, 2022). "The prevalence of hyperuricemia gradually increased from the first to the fourth RBP4 quartile from 5.0% to 58.2% (7.5% to 61.7% in males and 4.4% to 55% in females) (all P<0.001)." (PMID 35846279, 2022). "We also explored the predictive value of RBP4 combined with routinely assessed clinical factors that are related to hyperuricemia." (PMID 35846279, 2022). "More importantly, RBP4 was a good predictor of hyperuricemia; indeed, it performed better than traditional predictors." (PMID 35846279, 2022). "The optimum model for predicting hyperuricemia in the general population consisted of RBP4, sex (male), body mass index, serum creatinine, high-sensitivity C-reactive protein, fasting blood glucose, insulin, and alcohol consumption." (PMID 35846279, 2022). "The effect of hyperuricemia on the increase in serum RBP4 levels in relation to the two types of SSB intake was limited." (PMID 24475021, 2014).
hyperuricemia (continued). "Additionally, recent studies have indicated that circulating RBP4 levels were related to IR in people with hyperuricemia." (PMID 36670387, 2023). "This large-scale study aimed to explore the association between RBP4 and hyperuricemia in the general population, and to evaluate whether RBP4 can predict hyperuricemia." (PMID 35846279, 2022). "Additionally, no reports have described the predictive value of retinol binding protein 4 (RBP4) for hyperuricemia." (PMID 35846279, 2022). "Predictive value of RBP4 and other indicators for hyperuricemia in the general population." (PMID 35846279, 2022). "In addition, there were higher values of SBP, DBP, WC, BMI, TG, LDL, FBG, insulin, HOMA-IR, SCr, cystatin C, NAG, hs-CRP, IL-6, and RBP4 in the hyperuricemia group compared to the non-hyperuricemia group (P<0.05), but lower values of HDL, eGFR, and serum uric acid (P<0.001)." (PMID 35846279, 2022). "The mechanisms by which how RBP4 predicts hyperuricemia remain unclear." (PMID 35846279, 2022). "Moreover, hyperuricemia was inversely associated with advanced fibrosis in male CHC patients, it might explain, at least partly, why uric acid levels and male sex were positively associated with RBP4 levels in CHC patients." (PMID 33135589, 2020). "Hyperuricemia is likely to intensify the influence of HFCS-rich SSB intake on elevated TG levels, and in overweight and obese adolescents, high BMI may modify the action of fructose on higher circulating levels of RBP4." (PMID 24475021, 2014).
hypothyroidism (8 papers, 2018 to 2023). Abnormally low levels of thyroid hormone. "There were positive relationships between RBP-4 and related cardiovascular risk factors and with hypothyroidism, its sensitivity and specificity were 47.9% and 42.5% respectively." (PMID 33133591, 2020). "The association of hypothyroidism (overt and subclinical) with increased RBP-4 levels has also been reported." (PMID 33133591, 2020). "YDSK patients performed certain hypothyroidism symptoms such as sensation of chill, debilitation, edema, poor appetite, sexual dysfunction, which might closely linked to the increased RBP4 level in our experiments." (PMID 29520099, 2018). "Increased RBP4 concentrations were observed in patients with both subclinical and overt hypothyroidism compared to euthyroid individuals." (PMID 35448487, 2022). "In hypothyroidism, RBP4 correlated positively with the lipid profile, fasting glucose, insulin and HOMA-IR, while in Hashimoto thyroiditis it correlated with insulin and HOMA-IR." (PMID 35448487, 2022). "Previously, the levels of RBP4 in the serum and urine of patients with hypothyroidism were found to increase, which ultimately aligns with our study results." (PMID 33503180, 2021). "Multiple regression analysis revealed that the expression levels of RBP4 in rats that developed maternal hypothyroidism during pregnancy were significantly correlated with the levels of TSH secretion." (PMID 33503180, 2021). "The expression levels of PiC and RBP4 in the rats in the CON group were significantly lower than those in the rats from the hypothyroidism groups at P14 and P35." (PMID 33503180, 2021). "We assume that at the early damage stage, the renal mitochondria in the rats with maternal hypothyroidism during pregnancy were occluded and the expression level of RBP4 was increased." (PMID 33503180, 2021). "In the present study, we sought to investigate the effect of the RBP4/PiC/SIRT3 signaling pathway on mPTP opening in rats that suffered from hypothyroidism during pregnancy." (PMID 33503180, 2021). "RBP4 plays an important role in early renal mitochondrial damage and renal impairment in rats suffering from hypothyroidism during pregnancy." (PMID 33503180, 2021). "Based on our results, RBP4 plays an important role in early renal mitochondrial damage and renal impairment in rats with hypothyroidism during pregnancy." (PMID 33503180, 2021). "The pathogenesis of elevated RBP-4 in hypothyroidism is generally attributed to the role of adipose tissue as an endocrine organ capable of secreting a number of adipose-tissue-specific hormones that are involved in the regulation of insulin action." (PMID 33133591, 2020). "However, it remains unclear whether increased RBP4 are a cause or a result of hypothyroidism." (PMID 31278889, 2019). "RBP4 levels are higher in patients with clinical hypothyroidism and exhibit an obvious decrease after normalization of thyroid function." (PMID 29520099, 2018). "Therefore, RBP4 serves as an important factor during the prediction of early renal damage in rats that develop maternal hypothyroidism during pregnancy." (PMID 33503180, 2021). "Moreover, the RBP4/PiC/SIRT3 pathway was identified to be involved in the function of the renal mPTP of offspring rats with hypothyroidism during pregnancy." (PMID 33503180, 2021). "In summary, our findings demonstrate that the activation of the RBP4/PiC/SIRT3 signaling pathway could be involved in the regulation of the opening/closing of the renal mPTP in rats that develop maternal hypothyroidism during pregnancy." (PMID 33503180, 2021). "Therefore, we opted to use a rat model to determine the role of RBP4 in mPTP opening in offspring rats that suffered from hypothyroidism during pregnancy." (PMID 33503180, 2021). "RBP4 levels are higher in patients with clinical hypothyroidism than controls." (PMID 31956345, 2020).
hypothyroidism (continued). "In hypothyroid individuals, RBP4 correlated positively with TSH, and negatively with T3, which indicates a potentiation of the stimulating effect of hypothyroidism on RBP4 with its increase in severity." (PMID 35448487, 2022).
liver disease (8 papers, 2008 to 2025). "Taken together, critically ill patients with underlying liver disease had lower baseline RBP4 and TC levels than controls." (PMID 28588245, 2017). "The implications of retinol-binding protein-4 (RBP4) expression in critically ill patients with underlying liver diseases remain unclear." (PMID 28588245, 2017). "In critically ill patients with underlying liver disease, with a link to eGFRs, INRs and TC levels, the baseline RBP4 may serve as a marker for short-term mortality." (PMID 28588245, 2017). "In patients with chronic liver disease, serum retinol and RBP4 levels are often lower, and the magnitude of the decrease correlates to some extent with the severity of liver disease." (PMID 40767555, 2025). "At a later, more severe stage of liver disease, serum retinol/RBP4 levels steadily decrease since liver damage compromises liver vitamin A stores (activated stellate cells), and the liver cannot maintain constant serum retinol/RBP4 levels." (PMID 40767555, 2025). "RBP4, as an adipokine, is closely related to the severity of liver disease in patients with alcoholic cirrhosis." (PMID 34889069, 2022). "With the deepening of research, RBP4 has been shown to be involved in the occurrence and development of liver diseases." (PMID 34889069, 2022). "Considering our finding of a biphasic change in serum retinol/RBP4 levels upon induction of liver damage, it suggests that the different changes in serum retinol/RBP4 levels in patients suffering from liver disease might be due to differences in the duration and severity of disease stage." (PMID 40767555, 2025). "The baseline RBP4 levels could predict short-term (within 21 days of ICU admission), but not long-term (1-year) mortality in critically ill patients with underlying liver diseases." (PMID 28588245, 2017). "Elevated RBP4 serves as a potential marker for early NAFLD diagnosis, and total bilirubin is pivotal in multiple liver disease models, including as a predictor for advanced fibrosis and cholangiocarcinoma." (PMID 39891059, 2025). "In contrast to that, in CLD patients – irrespective of the kind of liver disease – there were no increased amounts of RBP4-L and RBP4-LL, thus supporting the relation between RBP4 isoforms and kidney function." (PMID 18752671, 2008).
Retinal dystrophy (8 papers, 2012 to 2025). Retinal dystrophy is an abnormality of the retina associated with a hereditary process. "Although very rare, a bi-allelic c.248 + 1G > A mutation that led to extremely low RBP4 serum levels caused retinal dystrophy and ocular coloboma." (PMID 35334893, 2022). "A homozygous splice site variant in RBP4 (c.111 + 1G > A) was found to cause retinal dystrophy and developmental abnormalities." (PMID 33790810, 2021). "Rare bi-allelic mutations (c.248 + 1G > A) of RBP4 were identified in a patient with retinal dystrophy and ocular coloboma." (PMID 33790810, 2021). "Pathogenic variants in RBP4 gene lead to reduced plasma RBP4 and all-trans-retinol concentrations and are associated with night blindness, microphthalmia, anophthalmia, coloboma, retinal dystrophy and acne vulgaris." (PMID 35162940, 2022). "Likewise, in humans, total loss of RBP4 is only associated with night blindness, retinal dystrophy and chorioretinal coloboma." (PMID 32365517, 2020). "The visual cycle pathway involving Rbp4 already demonstrates therapeutic promise, with high-dose vitamin A supplementation showing benefits in related retinal dystrophies." (PMID 40558514, 2025). "Here, aside from the diminished RBP4 levels in serum, retinal dystrophies (progressive and severe autosomal recessive retinitis pigmentosa) and developmental abnormalities were identified." (PMID 35334893, 2022). "The compound heterozygous mutations p.I59N and p.G93D (I41N and G74D in the cleaved RBP4 protein) were found to cause night blindness and modest retinal dystrophy without effects on growth." (PMID 35334893, 2022).
acute coronary syndrome (7 papers, 2014 to 2025). Signs and symptoms related to acute ischemia of the myocardium secondary to coronary artery disease. "Retinol-binding protein-4 (RBP-4) along with the lipid profile plays crucial roles in Acute coronary syndrome (ACS)." (PMID 32449048, 2020). "RBP4 has been recently identified as an HDL associated protein; it is demonstrated that in patients with acute coronary syndrome." (PMID 25479076, 2014). "Combining RBP4 with other biomarkers improves prognostic accuracy for adverse cardiovascular events, and an RBP4-based multimarker score has been proposed as a prognostic tool for patients with acute coronary syndrome." (PMID 40276651, 2025). "Regarding the individual outcome of MACEs, circulating RBP4 level was significantly associated with HF rather than cardiovascular death, which was different from a prior study that reported that total RBP4 level was a predictor of cardiac death in patients with stable CAD or acute coronary syndrome." (PMID 35369314, 2022). "Moreover, RBP4 has been recently identified as an HDL-associated protein; it is demonstrated that in patients with acute coronary syndrome, HDL shifts to an inflammatory profile, which can in turn, alter the protective effects of HDL on the atherosclerotic plaque." (PMID 25142320, 2014).